NKX2-2 (NK2 homeobox 2)
Diseases named in the same sentence as NKX2-2 in open-access papers (continued):
Sharing a sentence is not in itself a finding about the gene and the disease.
prostate carcinoma (3 papers, 2016 to 2023). A carcinoma that arises from epithelial cells of the prostate gland. "Here, we perform a computational prediction and identify a module of mutually exclusive transcriptional drivers, AR, HOXC6 and NKX2-2, which co-dysregulate a core set of metastasis-associated miRNAs in prostate cancer." (PMID 28397780, 2017). "Next, We examined whether the observed mutual exclusivity between AR, HOXC6 and NKX2-2 overexpression is specifically associated with prostate cancer, or represents an intrinsic property of tumorigenesis." (PMID 28397780, 2017). "However, knocking down LSD1 did not upregulate metastasis-associated miRNAs in either LnCAP cells or in RWPE-1 cells overexpressing AR, HOXC6 or NKX2-2, suggesting that other co-factors mediate the transcriptional repression of miRNAs in prostate cancer." (PMID 28397780, 2017). "Unfortunately, examining H3K27ac ChIP-seq data in multiple prostate cancer cell lines suggested that AR, HOXC6 and NKX2-2 are not broadly associated with super enhancers." (PMID 28397780, 2017). "The lack of synergy among AR, HOXC6 and NKX2-2 suggests that the three master TFs may indeed compete for a common epigenetic co-factor to inhibit miRNA expression in prostate cancer." (PMID 28397780, 2017).
B-cell lymphoma (2 papers, 2018 to 2019). "Our data assemble a pathological gene regulatory network surrounding NKX2-2 and extend the oncogenic role of NKL homeobox genes to this type of B-cell lymphoma." (PMID 30680064, 2018). "Dataset GSE40160 contains samples of primary mediastinal B-cell lymphoma (PMBL), revealing NKX2-2 overexpression in 1 of 5 (20%) PMBL patients." (PMID 30680064, 2018).
cervical carcinoma (2 papers, 2016 to 2020). A carcinoma arising from either the exocervical squamous epithelium or the endocervical glandular epithelium. "In particular, the cervix carcinoma produced high levels of NKX2-1, NKX2-2 and NKX2-5." (PMID 27876760, 2016).
depression (2 papers, 2019 to 2024). "In animal models of depression, naringenin treatment has been shown to upregulate BDNF, SHH, GLI1, NK2 Homeobox 2 (NKX2.2), and Paired box protein Pax-6 (PAX6)." (PMID 39478958, 2024).
diffuse large B-cell lymphoma (2 papers, 2019). "Furthermore, subsets of diffuse large B-cell lymphoma (DLBCL) and HL ectopically express the non-code members NKX2-1 and NKX2-2, respectively." (PMID 31141539, 2019).
metastatic prostate carcinoma (2 papers, 2017 to 2022). A carcinoma that arises from the prostate gland and has spread to other anatomic sites. "The central premise of our study is that the set of miRNAs co-regulated by AR, HOXC6 and NKX2-2 captures the majority of miRNAs associated with metastatic prostate cancer." (PMID 28397780, 2017).
type 2 diabetes (2 papers, 2015 to 2023). "Of the 132 type 2 diabetes Knowledge Portal effector genes, we identified 18 (14%) as candidate effector genes for at least one phenotype, including ABCC8, KCNJ11, NKX2–2, G6PC2, PAM, HNF4A, SLC30A8, RFX6, PCSK1, and GLIS3." (PMID 37333221, 2023).
cryptorchidism (1 paper, 2018). The failure of one or both testes of a male fetus to descend from the abdomen into the scrotum during the late part of pregnancy. "Following GnRHa treatment, NKX2-2 showed increased expression (log FC = 2.51, FDR = 0.0064), indicating a possible role for this homeobox gene in cryptorchidism-induced infertility." (PMID 30071651, 2018).
hemangioma (1 paper, 2021). A benign vascular lesion characterized by the formation of capillary-sized or cavernous vascular channels. "Also, recently reported novel markers for EWSR1-NFATC2-rearranged round cell sarcoma such as NKX2-2 and NKX3-15,6,11 were negative in the vascular malformations/hemangiomas with EWSR1-NFATC2 rearrangement and SBCs." (PMID 34081036, 2021).
leukemia (1 paper, 2019). A malignant (clonal) hematologic disorder, involving hematopoietic stem cells and characterized by the presence of primitive or atypical myeloid or lymphoid cells in the bone marrow and the blood. "Many of the predicted transcription factors have a known role in hematopoiesis and leukemia development (Ikzf2, Pbx3, and Hoxa13 for upregulated genes and Fos, Nkx2-2, Gata2 for downregulated genes)." (PMID 31186416, 2019).
lymphoid tumors (1 paper, 2019). "NKX2-2: Similar to NKX2-1, NKX2-2 is ectopically activated in lymphoid tumors, including T-ALL and HL." (PMID 31779217, 2019).
T-cell lymphoma (1 paper, 2021). "Of note, T-cell lymphoma cell lines DERL-2 and DERL-7 have been shown to aberrantly express NKX2-2 and were used here as controls." (PMID 34768865, 2021).
tumor (50 papers, 2010 to 2026). "Combinedly, these results indicated that TrkC may be a key mediator in ES tumorigenicity and acts through the upregulation of selected tumor-associated molecular markers, NKX2-2 and EGR2." (PMID 36171207, 2022). "Mutations in EE-015B enhanced GATA1 and NK2 homeobox 2 (NKX2-2) affinity, both genes related to tumor proliferation and oncogenic signaling." (PMID 41019514, 2026). "The spatial transcriptome data identified differential expression of DDX3Y, PGR and NKX2‐2 between tumour samples and normal samples." (PMID 39548559, 2024). "NK homeobox (NKX) genes, especially NKX2‐2, a tumor suppressor for OS, and overexpression of NKX2‐2 decreased the migration, invasion, proliferation and colony formation of OS cells." (PMID 31725956, 2020). "An assessment of the twenty-nine enteroendocrine-related transcription factors identified that ST18, INSM1 and NKX2-2 were commonly expressed in both tumor sets." (PMID 25023465, 2014). "Notably, NKX2-2 is a key transcription factor in forming core regulatory circuitry (CRC) to drive important signaling pathways for tumor development." (PMID 37759224, 2023). "Additionally, a positive correlation between NKX2-2 and m6A writers was found in different ES tumor datasets." (PMID 37759224, 2023). "Collectively, the results indicate that NKX2-2 regulates KIAA1429-associated m6A writers, facilitating the positive feedback loop between KIAA1429 and STAT3 and reinforcing ES-dependent epigenetic changes, the malignant cell cycle and tumor-triggered inflammation in ES." (PMID 37759224, 2023). "The tumor cells expressed CD99, synaptophysin, CD56, MUC4, and EMA (focal), but not AE1/AE3, S100, smooth muscle actin, desmin, CD34, chromogranin A, GFAP, NKX2-2, PAX7, and INSM1." (PMID 39249507, 2024). "Furthermore, our regulon analysis confirms a previous report that NKX2-2 transcription factor can be considered specific to PIT-1/SF-1 sPitNETs, as we observed the highest activity of NKX2-2 in this tumor subtype." (PMID 40813692, 2025). "In the present study, a signature for BRCA radiotherapy sensitivity prediction was developed based on the expression of six characteristic DEGs, including HOXB13, NKX2-2, ADAMTS20, LOC284930, ACTL8 and LOC101928978, in BRCA tumor samples compared with their paracancerous samples for the first time." (PMID 33179733, 2020).
cancer (16 papers, 2015 to 2025). A tumor composed of atypical neoplastic, often pleomorphic cells that invade other tissues. "Conversely, NK2 homeobox 2 (NKX2-2) and growth factor independent 1 (GFI1), both recognized for their cancer-suppressive roles, are preferentially associated with inhibitory elements." (PMID 40032852, 2025). "In our study, we further confirmed the highest expression level of NKX2-2 in ES in the pan-cancer analysis and confirmed nearly undetectable expression in other tumors." (PMID 37759224, 2023). "We ranked them by FC in expression (between ES and other cancer types), the results suggested that NKX2-2 might be an upstream regulator in the KIAA1429-mediated pathway with high ES specificity." (PMID 37759224, 2023). "Finally, the mutually exclusive overexpression between AR, HOXC6 and NKX2-2 is preserved across various tissues and cancers, suggesting that mutual exclusivity may represent an intrinsic characteristic of driver TFs during tumorigenesis." (PMID 28397780, 2017). "NKX2-2 is one of the downstream target genes of GLI1 in the Sonic hedgehog (Shh) signaling pathway, and impairment of this pathway can result in both birth defects and cancer." (PMID 33179733, 2020). "However, aberrant NKX2-2 expression was not identified in the group of HSTL patients analyzed here, suggesting that this oncogene is rarely activated in this cancer type." (PMID 31143370, 2019).
neurodevelopmental disorder (1 paper, 2023). A behavioral and cognitive disorder with onset during the developmental period that involves impaired or aberrant development of intellectual, motor, or social functions. "NKX2-2 also demonstrates the highest correlation in brain tissue (incongruent r = 0.71, p-value = 2.26−03), but is the only gene that was not replicated in any other neurodevelopmental disorder included in the analysis (plot not shown)." (PMID 37907504, 2023).
NKX2-2 also shares sentences with these, for which no sentence is quoted: synovial sarcoma (4 papers); lymphoma (3); MODY (3); neuroendocrine tumors (3); Obesity (3); astrocytoma (2); bone tumor (2); colorectal cancer (2); fibromatosis (2); lung carcinoma (2); medulloblastoma (2); pancreatic NETs (2); Wilms tumor (2); adamantinoma (1); angiosarcoma (1); astrocytic tumor (1); B-cell CLL (1); benign tumors (1); bladder carcinoma (1); brain tumors (1); chondroblastoma (1); clear cell sarcoma (1); CNS tumor (1); congenital hyperinsulinism (1); gastric NETs (1); giant cell tumor (1); infection (1); Infertility (1); Insulin resistance (1); invasive breast carcinoma (1).
A further 20 diseases each share a sentence with NKX2-2 in 1 paper.